ADA (adenosine deaminase)
Diseases named in the same sentence as ADA in open-access papers (continued):
Sharing a sentence is not in itself a finding about the gene and the disease.
anaplastic large cell lymphoma (1 paper, 2018). Anaplastic large cell lymphoma (ALCL) is a rare and aggressive peripheral T-cell non-Hodgkin lymphoma, belonging to the group of CD30-positive lymphoproliferative disorders, which affects lymph nodes and extranodal sites. "It has been reported that the CD26/ADA complex is selectively expressed on Hodgkin’s and ALK-positive anaplastic large cell lymphomas." (PMID 29497379, 2018).
ankylosing spondylitis (1 paper, 2023). An autoimmune chronic inflammatory disorder characterized by inflammation in the vertebral joints of the spine and sacroiliac joints. "NSAID (etoricoxib or etoricoxib equivalent) consumption during the trial study of biosimilar adalimumab (Bs-ADA) in the study of patients (n = 50) with symptomatic moderately severe chronic ankylosing spondylitis: a single-arm prospective observational study." (PMID 36960229, 2023).
aortic valve disease (1 paper, 2020). "To underline the causality between aortic valve disease and differential expression of adenosine-metabolizing ecto-enzymes, we performed an interventional experiment using adenosine deaminase inhibitor in our mouse model of CAVD." (PMID 31144065, 2020).
asthenozoospermia (1 paper, 2020). "Zinc supplementation restores UA levels and the activities of enzymes involved in the urate pathway (XO and ADA), in the seminal plasma and spermatozoa of patients with asthenozoospermia, to reference values." (PMID 31710193, 2020).
astrocytoma (1 paper, 2019). "While it remains to be explored if the astrocytoma cell line is deficient in FBXW7, these studies indicate a potential role for ADA as a therapeutic target." (PMID 31351478, 2019).
B cell deficiencies (1 paper, 2019). "These conditions include severe forms of B cell deficiencies such as XLA, with an approximate incidence of 1:100,000, but also some patients with late-onset adenosine deaminase deficiency (ADA) and purine nucleoside phosphorylase (PNP) deficiencies." (PMID 33072998, 2019).
B cell lymphopenia (1 paper, 2015). "The addition of KREC based screening would allow identification of concurrent B cell lymphopenia, including patients with delayed-onset ADA-SCID, however a systematic evaluation of the effectiveness of additional KREC screening is not available yet." (PMID 25893636, 2015).
bacteremia (1 paper, 2015). "Whereas mock-treated mice suffered high levels of bacteria in the lungs and blood, ADA-inhibited mice had on average ten thousand-fold fewer pneumococci in the lungs and were free of detectable bacteremia." (PMID 26313746, 2015).
bone marrow failure (1 paper, 2020). "This includes genes mutated in rare hematological syndromes (ADA, GP6, IL17RA, PRF1, and SEC23B), reported in prior MDS/AML or inherited bone marrow failure (IBMF) series (DNAH9, SH2B3, and NAPRT1), or novel loci where loss-of- function of the identified germline variants was demonstrated (DHX34)." (PMID 32098966, 2020).
brain tumors (1 paper, 2022). "In this study, we report that in a range of malignancies, including uveal melanoma and several types of aggressive brain tumors, high ADA expression or activity in cell line models is associated with a dramatically reduced therapeutic response to cordycepin." (PMID 35804893, 2022).
bronchioloalveolar carcinoma (1 paper, 2021). A well or moderately differentiated morphologic variant of lung adenocarcinoma characterized by tumor growth along the alveolar structures without stromal, vascular, or pleural invasion. "ADA, SqCC, Large cell carcinoma, Bronchioloalveolar carcinoma, Small cell carcinoma." (PMID 34797317, 2021).
cardiac hypertrophy (1 paper, 2014). "This previous study was performed using 1-day old RyR2ADA/ADA homogenates at a very early stage-of-onset of cardiac hypertrophy." (PMID 25093823, 2014).
cat-eye syndrome (1 paper, 2017). Cat eye syndrome (CES) is a rare chromosomal disorder with a highly variable clinical presentation. "Lastly, CECR1, which could only be analyzed with SKAT, encodes an adenosine deaminase (ADA2) and has been associated with Cat Eye Syndrome, Sneddon’s syndrome and Polyarteritis nodosa." (PMID 28814775, 2017).
cerebral malaria (1 paper, 2006). A sequestration of Plasmodium falciparum in the brain, which can cause coma and/or seizures. "CSF/serum ADA ratio was lower in patients with cerebral malaria due to the fact that serum ADA levels were significantly higher in patients with cerebral malaria compared to the other two groups." (PMID 16764711, 2006). "CSF ADA levels were measured in 3 patients with cerebral malaria previously, and found to have a mean (SD) of 6.6 (1.03) IU/l, slightly higher than the levels in our study (4.6 (0.9) IU/l)." (PMID 16764711, 2006). "CSF white cell count, protein and glucose levels and CSF/serum ADA ratio below these cut-off values indicated cerebral malaria with a sensitivity of > 90%." (PMID 16764711, 2006). "However, the CSF/serum ADA ratio was lower in patients with cerebral malaria due to the high levels of ADA in peripheral blood." (PMID 16764711, 2006). "Patients with cerebral malaria had significantly lower CSF glucose, and higher protein, LDH, CSF/blood LDH ratio and CSF ADA levels but a lower CSF/serum ADA ratio compared to controls (p < 0.01)." (PMID 16764711, 2006). "Patients with cerebral malaria had significantly higher CSF protein, LDH and ADA levels and CSF/serum LDH ratio but a lower CSF/serum ADA ratio, compared to controls." (PMID 16764711, 2006).
CHARGE syndrome (1 paper, 2024). CHARGE syndrome is a multiple congenital anomaly syndrome characterized by the variable combination of multiple anomalies, mainly Coloboma; Choanal atresia/stenosis; Cranial nerve dysfunction; Characteristic ear anomalies (known as the major 4 C's). "However, OS has also been described in other genetic aetiologies that impair lymphocyte development, including IL7RA, IL2RG, ADA, DCLRE1C, RMRP and LIG4 deficiencies, and CHARGE syndrome." (PMID 38598033, 2024).
chronic gastritis (1 paper, 2017). Inflammation of the stomach that is chronic in nature. "Based on this, the authors concluded that ADA activity does not seem to be a factor promoting chronic gastritis." (PMID 29018360, 2017). "In that study, ADA activity was measured in biopsies collected from patients infected with H. pylori that had developed chronic gastritis and that had been submitted or not to distal resection, as well as non-infected controls." (PMID 29018360, 2017).
chronic kidney disease (1 paper, 2022). Impairment of the renal function secondary to chronic kidney damage persisting for three or more months. "DIP doesn't affect ADA activity or expression of ADA-BP; however, a higher intra-lymphocytic concentration is linked with immune suppression in patients with chronic kidney diseases." (PMID 37521831, 2022).
chronic pancreatitis (1 paper, 2022). A chronic inflammatory process causing damage and fibrosis of the pancreatic parenchyma. "Moreover, ADA serum levels increased in healthy controls to patients with acute and chronic pancreatitis and finally in PDAC patients indicating that ADA may play a role in inflammatory processes of the pancreas." (PMID 36230528, 2022).
congenital combined immunodeficiency (1 paper, 2020). "Impaired ADA activity directly correlates with defective adenosine metabolism as shown in ADA-SCID, a severe, congenital combined immunodeficiency." (PMID 32438744, 2020).
coronary artery diseases (1 paper, 2009). "Recently it has been reported an association between adenosine deaminase genetic polymorphism and coronary artery diseases." (PMID 20428226, 2009). "A highly significant complex relationship has emerged among ADA, birth weight, and gender concerning their role on susceptibility to coronary artery diseases in adult life." (PMID 20428226, 2009).
cryptorchidism (1 paper, 2020). The failure of one or both testes of a male fetus to descend from the abdomen into the scrotum during the late part of pregnancy. "In summary, this report describes a high prevalence of cryptorchidism in a cohort of male ADA-SCID patients which could represent an additional systemic manifestation of ADA-SCID." (PMID 32307643, 2020).
dermatitis (1 paper, 2025). An inflammatory process affecting the skin. "Our cohort also included two patients with ADA and PEPD deficiencies presenting with associated dermatitis." (PMID 41357247, 2025).
diarrhoea (1 paper, 2023). "The increase in ADA found in our proteomic study was also confirmed in the larger population of pigs with diarrhoea with E. coli compared to healthy pigs, corroborating the higher levels of this protein in saliva in this disease, possibly reflecting activation of inflammation and the immune system." (PMID 37092455, 2023).
diffuse midline glioma (1 paper, 2022). A diffuse glioma that arises from the midline structures of the central nervous system. "Treatment with 160 μM cordycepin also increased cleaved PARP protein in low ADA active AT/RT (BT37) and diffuse midline glioma H3 K27-altered cells (JHH-DIPG1), consistent with an increase in apoptosis." (PMID 35804893, 2022). "In retinoblastoma, AT/RT, and diffuse midline glioma H3 K27-altered cells with low ADA, cordycepin significantly inhibited cell growth and increased apoptotic markers, including cleaved PARP, while those with higher ADA expression were more resistant." (PMID 35804893, 2022). "However, we did not detect cleaved PARP in high ADA AT/RT (BT12) and diffuse midline glioma cells (SS7761)." (PMID 35804893, 2022).
dry eye (1 paper, 2024). "Currently, antiviral drugs (type I IFN and cART) are combined with drugs for dry eye (artificial tears and corticosteroids) and anti-inflammatory drugs, such as ADA and IFX." (PMID 38047740, 2024).
dyschromatosis symmetrica hereditaria (1 paper, 2014). Acropigmentation of Dohi is a genodermatosis characterized by the presence of hyperpigmented and hypopigmented macules, principally located on the extremities and limbs. "Dyschromatosis symmetrica hereditaria (DSH) is an autosomal dominantly inherited skin disease associated with mutations of ADAR1, the gene that encodes a double-stranded RNA-specific adenosine deaminase." (PMID 24950769, 2014).
E. coli infection (1 paper, 2023). "In addition, the levels of adenosine deaminase, prealbumin, and CK in the E. coli infection group were significantly lower than those in the Gram-positive coccus infection group (p < 0.05)." (PMID 38066783, 2023).
emphysema (1 paper, 2023). "In the realm of COPD, a mouse model of airspace enlargement as seen in emphysema, is generated by adenosine deaminase (ADA) deficiency." (PMID 36986517, 2023).
endotoxemia (1 paper, 2024). "A well-defined murine model of endotoxemia permitted the identification of the origin and extent of A-to-I editing, along with temporally discrete signatures of double-stranded RNA stress and adenosine deaminase isoform switching." (PMID 38954486, 2024).
fibromyalgia (1 paper, 2020). A chronic disorder of unknown etiology characterized by pain, stiffness, and tenderness in the muscles of neck, shoulders, back, hips, arms, and legs. "Disturbed adenosine homeostasis in the subcutaneous tissue may happen upon infiltration by ADA-bearing inflammatory cells and/or in situations occurring with increases in serum ADA levels, such as fibromyalgia and other chronic inflammatory conditions." (PMID 32156055, 2020).
food allergy (1 paper, 2024). Gastrointestinal disturbances, skin eruptions, or shock due to allergic reactions to allergens in food. "While development of food allergy is likely related to an underlying genetic or environmental risk, we cannot exclude the possibility that it may signify immune dysregulation which can occur in patients with ADA deficiency." (PMID 38676811, 2024).
gastric tumours (1 paper, 2019). "Low ADA activity was found in prostate and gastric tumour tissues and in lymphocytes of patients suffering from different pathologies, such as gynaecological, renal, head and neck, and gastric tumours, as well as Hodgkin’s lymphoma." (PMID 31547393, 2019).
gastric ulcer (1 paper, 2025). An ulcerated lesion in the mucosal surface of the stomach. "Our results were very close to those obtained in a previous clinical study, in which ADA and S100A12 were quantified in horse saliva, and whose ROC analysis also showed moderate accuracy in differentiating healthy horses from those with gastric ulcer (AUC of 0.84 for each)." (PMID 40805041, 2025).
gram-negative bacterial infections (1 paper, 2016). Infections caused by bacteria that show up as pink (negative) when treated by the gram-staining method. "This low ADA activity may be a protective factor against Gram-negative bacterial infection of the pleural space." (PMID 27276396, 2016). "The results indicated that lowering ADA activity may be a novel and viable therapeutic approach to managing Gram-negative bacterial infection." (PMID 27276396, 2016).
head and neck squamous cell carcinoma (1 paper, 2021). A squamous cell carcinoma that arises from any of the following anatomic sites: lip and oral cavity, nasal cavity, paranasal sinuses, pharynx, larynx, and salivary glands. "In fact, ADA deficiency has been shown to result in tumor progression, and ADA activity of T cells has been suggested as an indicator of immune competence in patients with head and neck squamous cell carcinoma." (PMID 34095230, 2021).
Headache (1 paper, 2023). Cephalgia, or pain sensed in various parts of the head, not confined to the area of distribution of any nerve. "The occurrence of headache was defined as a dependent variable and the independent variables included DBP, SBP, NHISS, WBC, L, LR, MCV, USG, ICP, levels of HBs-Ab, BUN, protein (CSF), ADA (CSF), LDH (CSF), CI- (CSF), and NHISS (at discharge)." (PMID 36732686, 2023).
Hematuria (1 paper, 2024). The presence of blood in the urine. "With the exception of ADA development and hematuria, all emicizumab-related events were successfully resolved." (PMID 38812987, 2024).
hyperlipidemia (1 paper, 2016). "ADA in adipose tissue causes the increase in lipolysis, the augmentation of hyperlipidemia, and the disturbance in antilipolysis activity." (PMID 28050278, 2016).
hypophosphatemia (1 paper, 2021). Lower than normal levels of phosphates in the circulating blood. "This may be because low serum phosphate levels strongly induce DNA damage and contribute to the release of purine nucleotides; the degradation of AMP to inosine monophosphate by adenosine deaminase in hypophosphatemia may accelerate the synthesis of uric acid." (PMID 34444197, 2021).
hypothyroidism (1 paper, 2012). Abnormally low levels of thyroid hormone. "Strikingly, ADA−/− mice treated with PEG-ADA developed multiple autoantibodies and hypothyroidism in contrast to mice treated with HSC-GT or BMT." (PMID 22969765, 2012).
Intellectual disability (1 paper, 2021). "Notably, a polymorphism in the ADA1 gene in autistic children with mild intellectual disability has been found to be associated with reduced ADA activity in serum." (PMID 34054547, 2021).
intracranial haemorrhage (1 paper, 2021). "Compared with MDR bacteria-negative patients, MDR bacteria-positive patients more frequently underwent surgery, had external ventricular drainage/lumbar cistern drainage, were complicated with intracranial haemorrhage, and had elevated levels of CSF ADA, protein and leukocytes." (PMID 34404351, 2021).
Jaundice (1 paper, 2022). Yellow pigmentation of the skin due to bilirubin, which in turn is the result of increased bilirubin concentration in the bloodstream. "Previous studies have reported increases in the biochemical markers MDA, ADA, ALT, ALP, DBIL, TBIL, TBA, and γ-GT in clinical jaundice, whereas the levels of PAB, T-SOD and GSH-Px were decreased." (PMID 35450037, 2022).
junctional epidermolysis bullosa (1 paper, 2018). "Examples include ADA-deficiency treatment with genetically modified CD34+ blood cells or junctional epidermolysis bullosa therapy with LM5-beta 3-transduced epidermal cells, after approximately 10 years of follow-up in both cases." (PMID 30221121, 2018).
Kabuki syndrome (1 paper, 2023). Kabuki syndrome (KS) is a multiple congenital anomaly syndrome characterized by typical facial features, skeletal anomalies, mild to moderate intellectual disability and postnatal growth deficiency. "Hearing loss can be a clinical manifestation in patients with Kabuki Syndrome, glucose‐6‐phosphatase enzyme (G6PC3) deficiency, Reticular Dysgenesis, and ADA deficiency." (PMID 37102642, 2023).
latent infection (1 paper, 2013). "The altered responses prompted us to characterize the expression of adenosine receptors, the adenosine generating enzyme CD73, and the adenosine catabolizing enzyme ADA in rat ileum during HSV-1 latent infection of ENS." (PMID 24015268, 2013).
learning disability (1 paper, 2023). A group of disorders that affect a person's ability to learn or process specific types of information which is in contrast to his/her apparent level of intellect. "These neurological manifestations in ADA-SCID are caused by variants to the ADA gene that result in accumulation of toxic metabolites in the brain particularly the thalamus and basal ganglia, leading to neurological function abnormalities such as motor abnormalities and learning disability." (PMID 37781398, 2023).
Leber congenital amaurosis (1 paper, 2019). Leber congenital amaurosis (LCA) is a retinal dystrophy defined by blindness and responses to electrophysiological stimulation (Ganzfeld electroretinogram (ERG)) below threshold, associated with severe visual impairment within the first year of life. "Notably, it has been able to treat beta thalassemia, Leber's congenital amaurosis, severe immunodeficiency diseases such as ADA-SCID, and more." (PMID 31069169, 2019).
Leukoencephalopathy (1 paper, 2017). This term describes abnormality of the white matter of the cerebrum resulting from damage to the myelin sheaths of nerve cells. "Brain MRI revealed leukoencephalopathy, enlargement of ventricles and subarachnoid spaces in all three groups of ADA-SCID patients." (PMID 28074903, 2017).
Lipedema (1 paper, 2022). Disorder of adipose tissue characterized by symmetric and bilateral enlargement of the lower extremities due to abnormal deposition of subcutaneous fat often in obese women. "Further studies are needed to understand whether the most different inflammatory markers between these groups (TNFSF14, CASP8, EN-RAGE, EIF4EBP1, ADA, MCP-1) play a mechanistic role in lipedema development and perpetuation." (PMID 36387874, 2022).
liver abscesses (1 paper, 2025). "The patient, SCID3 having ADA mutations presented with lung and liver abscesses and CMV infection." (PMID 40457861, 2025).
liver dysfunction (1 paper, 2022). "According to the ROC curve analysis, the sensitivity and specificity of ADA activity as a diagnostic marker to distinguish AOSD related liver dysfunction and non-AOSD related liver dysfunction were both 93.3%, and area under the ROC curve was 0.94." (PMID 35090387, 2022).
lymphadenitis (1 paper, 2024). Acute or chronic inflammation of one or more lymph nodes. "In contrast, another study from Bangladesh demonstrated raised serum ADA levels in only 4/10 (40%) TB lymphadenitis and 34/36 (94%) of TB pleuritis patients, however, the low number of lymphadenitis patients could explain the smaller proportion with raised ADA levels in this study." (PMID 39623309, 2024). "In patients with TB lymphadenitis, ferritin levels were raised in 6/47(13%), CRP in 10/47 (21%), and ADA in 33/47 (70%) of cases." (PMID 39623309, 2024). "When analyzed separately, levels of ferritin (p = 0.046) and CRP (p = 0.017) decreased significantly only at 6 months of treatment, while, ADA levels did not decease at any time point among TB lymphadenitis patients." (PMID 39623309, 2024). "This was expected as ADA levels did not decrease with treatment in lymphadenitis patients." (PMID 39623309, 2024).